CXCL12 (C-X-C motif chemokine ligand 12)
Diseases named in the same sentence as CXCL12 in open-access papers (continued):
Sharing a sentence is not in itself a finding about the gene and the disease.
tumor (continued). "Taken together with the results of our co‐culture experiments, these observations suggest that tumor cell invasion into muscle tissues may lead to CXCL12 upregulation in muscle cells." (PMID 36300800, 2023). "By contrast, grade 3 tumors showed disseminating single cell invasion into the muscularis propria, which caused disruption of the muscle structure and a decrease in muscle cell numbers and eventually led to a reduction in CXCL12‐positive areas within the tumor tissues." (PMID 36300800, 2023). "Moreover, CAFs impaired anti-tumor T cell immunity, through CXCL12-mediated T cell exclusion and/or TGFβ-mediated T cell functional suppression." (PMID 37771596, 2023). "Next, we describe the role of CXCL12 and its receptors in tumor progression." (PMID 37497001, 2023). "Infiltrated immune cells shift their phenotypes from anti-tumor, also known as pro-inflammatory phenotypes, to pro-tumor phenotypes because tumor cells increase interleukins and chemokines such as IL-2, IL-4, IL-6, IL-7, IL-10, IL-12, and CXCL12 concentrations." (PMID 37533070, 2023). "In addition to its influence on cancer–neuronal crosstalk and tumor growth, the CXCL12/CXCR4 axis is also important for immune cell migration and possibly plays a role in modulating the response to immunotherapy." (PMID 37834436, 2023). "A tissue microarray was constructed to evaluate the CXCL12 immunostained tumor tissue." (PMID 37966614, 2023). "CAFs produce angiogenesis regulators, such as VEGFA, PDGFC, FGF2, CXCL12, osteopontin, and CSF3 to promote the growth of tumor-associated blood vessels by recruiting myeloid cells and accelerate tumor angiogenesis by attracting vascular endothelial cells and recruiting monocytes." (PMID 37784082, 2023). "Additionally, CXCL12 is involved in cell homing, angiogenesis, immune and inflammatory responses, tumor infiltration, and metastasis." (PMID 38035102, 2023). "CXCL12 is constitutively released in various organs, including the lung, brain, liver, skeletal muscle, heart, skin, kidney and bone marrow, and it promotes ischaemic tissue revascularization and tumour development." (PMID 37162544, 2023). "More recently, tumour cell migration and metastasis as functions of CXCL12, have been confirmed." (PMID 37170733, 2023). "Furthermore, CAFs can also limit CD8 + T cell recruitment and infiltration by producing IL-6, TGF-β, and CXCL12, and inhibiting their cytotoxic capabilities against tumor cells." (PMID 37723510, 2023). "Our data suggest that RB could repress PI3K/AKT/mTOR signaling pathway and autophagy to block the CXCL12 expression in CAFs, thereby weakening the CXCL12-mediated EC tumor progression." (PMID 37029408, 2023). "Furthermore, immunohistochemistry (IHC) demonstrated that BF-TK/GCV reduced the expression of HIF−1α, mTOR, NF-κB1-p105, VCAM1, MMP13, CXCL12, ATG16, and CEBPB, which were associated with tumor metastasis." (PMID 37511481, 2023). "Similarly, CXCL11, CXCL12, and CXCL13 encoded the C-X-C motif chemokine ligands, critical regulators of tumor progression in many cancers." (PMID 37537613, 2023). "On one hand, these microparticles recruit monocytes producing IFN-γ and IL-4, which are involved in the tumoricidal function of macrophages, via the chemoattractants RANTES/CCL5, MIF (macrophage migration inhibitory factor), CCL2 and CXCL12; thus, they suppress primary tumor growth." (PMID 36831450, 2023). "Indeed, the presence of CXCR4 overexpression strengthens the ability of several tumor types to migrate and metastasize into organs while also secreting high levels of CXCL12, a known attractant of cancer cells." (PMID 36980182, 2023). "Collectively, these data suggested that CXCL12 had a strong tumor-promoting effect and could affecting PDL1 expression." (PMID 38001512, 2023). "Our results suggest that tongue OSCC cells activate CXCL12 expression in muscle cells, which may contribute to tumor progression." (PMID 36300800, 2023).
tumor (continued). "Given the ease of access to peripheral blood versus tumor tissue, the circulating cytokine CXCL12 may be considered the first test in the clinical setting to assess biomarkers." (PMID 37359565, 2023). "Subsequent analysis showed that B cells expanded and matured into plasma cells within the TLS, migrated to tumor foci under the guidance of CXCL12+ fibroblasts, and exhibited high secretion of IgG and IgA antibodies targeting tumor cells, thereby promoting antitumor effects." (PMID 37632718, 2023). "CXCL12 is a chemokine that plays a critical role as a chemoattractant in the tumour niche." (PMID 37509322, 2023). "In addition, the potential of tumor expression of CXCL12 as a biomarker for indicating adjuvant chemotherapy was also evaluated." (PMID 37227446, 2023). "Moreover, resistance to immunotherapy, due to reduced tumor infiltration of cytotoxic T-lymphocytes or increased infiltration of MDSCs, was induced by CXCL12 signaling in vitro and in vivo, resulting in further promotion of tumor growth." (PMID 36725964, 2023). "Furthermore, in many kinds of cancers, the C-X-C motif chemokine ligand 12 (CXCL12)/CXCR4 axis plays a role in tumor formation and metastatic dissemination." (PMID 36003502, 2022). "The tumor-promoting mechanisms reported for these receptors include the proliferation of malignant cells, angiogenesis, local invasion, homing of disseminated tumor cells to CXCL12-rich sites of metastasis, and establishment of immunosuppressive tumor environments." (PMID 35681470, 2022). "The movement of cancer cells toward CXCL12 in metastatic sites is determined by the gain of CXCR4 expression and the loss of CXCL12 on the primary tumor at the same time, enabling movement of tumor cells, along with the CXCL12 gradient, toward the metastatic niche." (PMID 35203510, 2022). "Upregulation of immune checkpoint proteins, such as PD-1, CTLA-4, and T-cell immunoglobulin mucin-3 (TIM-3), and of transcripts IL8 and CXCL12, concomitant with downregulation of granzyme B and perforin in tumor MAIT cells, indicates that MAIT cells are exhausted and pro-tumor in HCC." (PMID 36551916, 2022). "To assess the involvement of these signaling molecules in chemokine-induced migration of the various tumor cells, we tested CXCL12- and CXCL11-dependent chemotactic responses in the presence of the Erk inhibitor, PD98059, the PI-3 K inhibitor, Ly294002, and the p38 inhibitor, SB203580." (PMID 36539774, 2022). "TEMs express the chemokine receptor CXCR4 and can be attracted into tumours by CXCL12." (PMID 36497114, 2022). "Tumor-infiltrating stroma cells were CXCL12 positive in only 15/76 (19.7%)." (PMID 36359736, 2022). "Cluster S1, described as “immune” stromal cells, were found early in tumour progression and showed high CXCL12 levels suggesting this might be a driver of early CAF T cell interaction during tumour progression." (PMID 35479076, 2022). "CXCL12 secretion also influences the transformation of tumor cells to mimic blood vessels." (PMID 35155581, 2022). "Numerous previous studies have indicated that neutrophils accumulate in the tumor microenvironment or metastatic niche to promote tumor metastasis, and that alveolar ECs are able to recruit neutrophils by secreting CXCL1, CXCL2, CXCL5 and CXCL12 after tumor-derived exosomal RNA stimulation." (PMID 36612175, 2022). "The addition of AMD3100 allowed for the release of these cells – and by analogy, the addition of AMD3100 to individuals with cold tumors could release them from the CXCL12 block at the periphery of tumors allowing their infiltration deeper in the tumor." (PMID 36341428, 2022). "EPCs are attracted by the CXCL12 gradient into a tumor’s hypoxic microenvironment." (PMID 35203510, 2022). "Additionally, CXCL12 recruits regulatory T cells to the tumor site, which act to suppress the immune response." (PMID 35567670, 2022). "High CXCL12 was also detected in tumor emboli and perineural infiltration." (PMID 36359736, 2022).
tumor (continued). "The CXCL12 chemokine system regulates tumor formation and progression in numerous organs." (PMID 36539774, 2022). "Interestingly, also the administration of CXCL12 to co-culture of mesothelioma cells with BM-isolated macrophages, leads to enhanced ingestion of tumor cells." (PMID 36293358, 2022). "Moreover, CXCL12 supports the recruitment of TAMs into the lungs, which promotes secondary tumor growth and angiogenesis." (PMID 35203510, 2022). "In particular, after a short recapitulation of background information, we will discuss the activities of CXCR4 and CXCL12 in the tumor microenvironment and the ability of CXCR4 to interact laterally with other receptors and to modulate processes that can be exploited in the context of immunotherapy." (PMID 35565443, 2022). "The dual blood supply in the liver, the anatomy of sinusoidal spaces, and the high CXCL12 expressing sinusoidal endothelial cells together facilitates circling tumor cells with CXCR4 expression adhere and extravasate into the liver parenchyma and establish distant organ metastases." (PMID 35145271, 2022). "Thus, targeting the CXCR4/CXCL12 axis can optimize intratumoral T cell localization, promote T cell anti-tumor activity, and enhance the efficacy of ICB and cytotoxic chemotherapy." (PMID 33603130, 2022). "These patterns are relevant in situations where the primary tumor expresses CXCL12." (PMID 35406582, 2022). "CXCL12 and its receptor CXCR4 have been implicated in tumor growth and metastasis in a variety of cancers, and CXCL12 expression has been observed in the tumor microenvironment and cancer cell cytoplasm and plasma membranes, but not focused on the plasma membrane 7-10." (PMID 34976180, 2022). "As an example, in prostate cancer, the transfer of pyruvate kinase 2 from the primary tumor to bone marrow stromal cells results in the increased expression of CXCL12 in the bone marrow in an HIF1α-dependent manner, favoring the establishment of metastatic cells in bone." (PMID 36497411, 2022). "Furthermore, the CXCL12/CXCR4 axis is also critical for tumor cell metastasis and drug resistance in cancer therapy." (PMID 35702353, 2022). "Notably, ligand/receptor pairs such as Il33/Il1rl1 (St2) and Cxcl12/Cxcr4 not only were abundant in tumors but also detected in cultured tumor cells." (PMID 35902768, 2022). "In addition, CAFs nourish CXCR4+ pancreatic cancer stem cells by producing its ligand CXCL12, promoting tumor cell growth and gemcitabine resistance via activation of FAK, AKT and ERK signaling pathways." (PMID 36230914, 2022). "CXCL12 and CXCR4 are expressed at significantly increased levels in gastrointestinal cancers, and this overexpression is associated with the activation of downstream pathways and survival, proliferation, angiogenesis, and migration of tumor cells." (PMID 35877436, 2022). "Therefore, we first evaluated the association of CXCL12, CXCR4, and FAPα mRNA expression with immune cell infiltration and procancer pathways in LARC using the Tumor IMmune Estimation Resource (TIMER) database and GSEA." (PMID 34976180, 2022). "Additionally, CXCL12 can act on tumor cells via CXCR4, promoting tumor cell proliferation and dissemination." (PMID 36612058, 2022). "One of the potential mechanism is that CXCL12 may prevent tumor infiltrating lymphocytes from migrating close enough to lead to cell death." (PMID 34976180, 2022). "Increased CXCL12 expression in hypoxic tissues is important for the homing of tumor stem cells in circulating tissues, CAFs secrete CXCL12, attract CXCR4-expressing tumor cells and endothelial progenitor cells, thereby promoting angiogenesis in the liver’s pre-metastatic niche." (PMID 35965504, 2022). "The mechanism may be related to the down-regulation of the CXCR4/CXCL12 signaling pathway in tumor tissues." (PMID 35814470, 2022).
tumor (continued). "Compared to normal tissue, gene expression analysis of DCIS tissue revealed the RNA expression of chemokines CXCL14 and CXCL12 is elevated in myoepithelial cells and fibroblasts, respectively, both of which directly bind to receptors on the tumor cells to induce cell migration." (PMID 35567670, 2022). "Studies have shown that CCL7, CXCL8 and CXCL12 also recruit m-MDSCs to tumor sites." (PMID 35493517, 2022). "In addition, inhibition of the interaction between CXCL12 and CXCR4 promoted T cell accumulation in central tumor areas and increased the effect of immune checkpoint blockade, suggesting that CXCL12 promotes spatial elimination of T cells." (PMID 36010986, 2022). "Alternatively, the high expression of CXCL12 in the tumor site can also be used to our advantage." (PMID 36231109, 2022). "CXCL12 could also mediate the trafficking of normal and tumor cells by binding to CXCR7, and the CXCL12/CXCR7 axis is involved in lymph node and liver metastasis of GC." (PMID 35647303, 2022). "Moreover, CXCL12 also affects the tumour microenvironment, and its combination with IL-6 can mediate the homing and proliferation of tumour cells." (PMID 36312898, 2022). "CXCL12 is a kind of tumor chemokine and plays an important role in tumor growth and metastasis." (PMID 36101803, 2022). "Furthermore, myofibroblasts sequester CD8+ T cells to prevent them from attacking tumor cells via the CXCL12/CXCR4 signaling pathway." (PMID 35972800, 2022). "In addition, CXCL12 has been shown to recruit suppressive MDSCs and pDCs at tumor sites and induce intra-tumor regulatory T cell (Tregs) localization, thereby impeding the immune machinery of ovarian cancer destruction." (PMID 36437919, 2022). "Clinically, manipulation of CXCL12/CXCR4 axis-mediated responses may contribute to the inhibition of CAF infiltration in ESCC tumor mass." (PMID 35941662, 2022). "The sequential treatment with an OV followed by CKM resulted in the upregulation of Th1-attracting cytokines (CKs) and reduction of Treg-attracting CKs (CCL22 and CXCL12), concurrent with enhanced trafficking of tumor-specific CD8+ T cells and NK cells into the TME." (PMID 36221123, 2022). "CXCR4 downregulation or blocking of the CXCR4/CXCL12 signaling pathway inhibits tumor metastasis." (PMID 35910383, 2022). "Our analysis of VEGF and CXCL12 levels in tumours from Atf4WT/WT and Atf4Δ/Δ mice revealed that the levels of these cytokines were decreased in the perivascular areas of tumours grown in Atf4Δ/Δ mice, and vCAFs appear to be the main source of angiogenic factors in the perivascular areas." (PMID 35654839, 2022). "The CXCL12/CXCR4 pathway is also implicated in the activation of CD44+/CD133+ prostate progenitor population, a drug-resistant population of cells that lead to tumor relapse and affects differentiation potential, cell adhesion, clonal growth and tumorigenicity of PCa cells." (PMID 35406450, 2022). "To determine whether CXCL12 participate in FGFR2+ fibrocyte recruitment, we first established whether a CXCL12 gradient existed between ESCC tumor mass and peripheral blood by ELISA." (PMID 35941662, 2022). "CXCL12/CXCR4 chemokine axis participates in tumor progression and metastasis." (PMID 35395810, 2022). "Activation of CXCL12/CXCR7 biased signal pathway may be critical for tumor progression by promoting cancer cell invasion and stem cell phenotype." (PMID 36210463, 2022). "In most lung cancer types, the CXCL12/CXCR4 axis is tumor-promoting." (PMID 36164329, 2022). "However, the addition of CXCR4 overexpression and CXCL12 further enhanced the increased migration capacity of SK-Hep1 cells induced by tumor-derived DNA." (PMID 35860597, 2022). "Finally, expression and signaling of the CXCR4/CXCL12 axis in both immunosuppressive and effector immune cells regulate the balance of pro- and antitumor leukocytes recruited to a tumor." (PMID 36293358, 2022). "Conversely, CXCL12 has also been described as an anti-tumor molecule in pancreatic cancer." (PMID 35406582, 2022).
tumor (continued). "The levels of CXCL4 and CXCL12 can be further elevated in cancer patients leading to micromolar concentrations at the tumor or metastasis site that could favor CXCL4–CXCL12 heterodimerization in vivo." (PMID 36229490, 2022). "CXCL12 is also described to be involved in tumor growth, angiogenesis and tumor cell intravasation." (PMID 36699696, 2022). "CXCL12 addition to tumor cells also induces the release of damage associated molecular patterns such as ATP, HMGB1 and calreticulin; in turn, HMGB1 can promote the secretion of CXCL12." (PMID 35565443, 2022). "Interestingly, in co-cultured Huh7 cells, radiation-induced CXCL12 mRNA seems to be larger than that of single cultured cells, indicating that co-culture of tumor and normal cells is beneficial to tumor survival." (PMID 35628460, 2022). "Moreover, MM cells recruit tumor-supporting macrophages by the CXCR4/CXCL12 axis and drive their polarization towards the M2 phenotype." (PMID 35958625, 2022). "Under inflammatory conditions, neutrophils release a variety of cytokines, one of which is CXCL12, which was significantly elevated in tumor supernatant from B16.BL6-bearing mice that had been treated with anti–CTLA-4 and 7HP349, for which chemokine receptor CXCR4 is expressed on CD8+ Teffs." (PMID 35552271, 2022). "IGS can be then envisaged as a survey process that exposes tumor tissues to immunosurveillance: in a small percentage of cases, this event leads to tumor rejection and antitumor immunity; in a large percentage, instead, the tumor-promoting activity of the CXCL12/CXCR4 axis prevails." (PMID 36293358, 2022). "Moreover, a high concentration of CXCL12-induced tumour dormancy contributes to drug resistance, arousing the clinical value of controlling CXCL12 production and scavenging excessive CXCL12 in the bone marrow." (PMID 36307871, 2022). "Multiple cytokines and chemokines, including CXCL12, CXCL16, interleukin (IL)-1β, IL-6, IL-34, macrophage colony-stimulating factor (M-CSF), and tumor necrosis factor-α (TNF-α), are also associated with tumor progression and hearing disturbance." (PMID 35628268, 2022). "Exploratory in vitro studies in the context of tumor immunotherapy have shown that CX-01 may also interfere with the CXCL12/CXCR4 axis." (PMID 35053249, 2022). "Finally, to explore the involvement of MMP9 in angiogenic and invasive processes, we concomitantly analyzed the baseline plasma expression of five related factors implicated in the tumor microenvironment: MMP2, VEGFA, VEGFR2, CXCR4, and CXCL12." (PMID 34980260, 2022). "Our study used CXCR4 and CXCL-12 to model the tumor microenvironment versus drug response." (PMID 36551144, 2022). "Among the factors secreted by primary tumor cells in response to hypoxia, CXCL12 could be an interesting factor because other functions are known to be exerted in the premetastatic niche when CXCL12 is secreted locally." (PMID 36497411, 2022). "Furthermore, in vitro assays have shown CCL2-secreting CAFs (or CAF-0s) attract tumor-associated THP-1 macrophages, while CXCL12-secreting CAFs (or CAF-1s) can attract monocytes and trigger their differentiation into M2-like macrophages." (PMID 36671452, 2022). "To determine whether CXCL12 is also altered in TEC in other tumor types, we performed a cross tumor meta-analysis." (PMID 35717322, 2022). "CXCR4 activates tumor metastases and its ligand CXCL12 is substantially generated." (PMID 36211359, 2022). "The role of CXCL12 in tumor development mainly depended on the specific microenvironment of tumors." (PMID 36419891, 2022). "Here we tested growth related markers which were primarily expressed by stromal cells including L-NGFR/CD271, p-ERK1-2 and CXCL-12, and found that the density of positive cells for each marker was progressively increased in line with the Gomori’s silver staining-based tumor grades." (PMID 35356507, 2022).